NES (nestin)
Diseases named in the same sentence as NES in open-access papers (continued):
Sharing a sentence is not in itself a finding about the gene and the disease.
glioma (continued). "To further demonstrate the role of this pathway in glioma progression, we established Nestin knockdown LN229/T98G cells." (PMID 33408794, 2021). "Together, these results suggested that the integrin αvβ3/CDC42/F-actin/YAP-1/NUPR1/Nestin signaling pathway was activated in 3D collagen/FN cultured glioma cells and induced glioma cell proliferation." (PMID 33408794, 2021). "Our data indicated that nestin+ glioma cells and endothelial cells contributed to PpIX fluorescence." (PMID 33959713, 2021). "Taken together, our findings suggest that the density of PpIX+ cells in lower-grade gliomas grows exponentially as the density of nestin+ glioma cells increases." (PMID 33959713, 2021). "Of note, activation of AKT (protein kinase B), which is negatively regulated by PTEN, correlates with Nestin expression in the perivascular niche, the location of residing glioma stem cells." (PMID 34681783, 2021). "Patient-derived glioma cells were characterized by immunofluorescence using Nestin, a neural progenitor marker, SOX2, a marker for pluripotency and self-renewal, and astrocytic marker GFAP confirms cells of glial origin in the culture." (PMID 34489494, 2021). "In lower-grade IDH1mut gliomas, we found that the number of PpIX+ putative glioma increased with the number of nestin+ cells (slope = 0.04 ± 0.01, R2 = 0.65, P = .03, n = 7 IDH1mut gliomas)." (PMID 33959713, 2021). "Several oHSV use the nestin promoter, including rQNestinv.2, which is set to complete a Phase 1 clinical trial in July 2021 for the treatment of recurrent glioma." (PMID 34372614, 2021). "We examined the SOX2 and Nestin expression in SOX2 or Nestin knockdown glioma cells cultured in the 3D collagen/FN system." (PMID 33408794, 2021). "Our data indicated that the PpIX+ cells in PpIX hotspots were a combination of nestin+ glioma cells and endothelial cells." (PMID 33959713, 2021). "We found that the density of PpIX+ cells grew exponentially with the density of nestin+ cells (slope = 0.002 ± 0.0004, R2 = 0.78, P = .008, n = 7 IDH1mut gliomas)." (PMID 33959713, 2021). "We found that the densities of PpIX+ cells increased exponentially with the density of nestin+ cells in lower-grade gliomas." (PMID 33959713, 2021). "The expression of Nestin was upregulated in SOX2 knockdown glioma cells, sand, conversely, SOX2 was upregulated in Nestin knockdown glioma cells." (PMID 33408794, 2021). "In regards of the glioma stem cell markers, we observed a high Nestin staining in all L0627 tumor samples and positive staining for Iba1 within and in the peripheral areas of the tumor and in cerebral hemisphere contralateral to tumor implantation." (PMID 34012924, 2021). "The PpIX hotspots in lower-grade glioma tissue contained nestin-positive (nestin+) glioma cells and endothelial cells." (PMID 33959713, 2021). "There is a hierarchal organisation of cancer cells, of which cancer-stem cells have been implicated in driving cancer progression, with the expression of CSC markers, such as nestin, being correlated with glioma malignancy." (PMID 33637089, 2021). "Nestin, an intermediate filament protein highly expressed in high grade gliomas, such as anaplastic astrocytoma and glioblastoma." (PMID 33391433, 2021). "Instead, this vector carries one copy of RL1 gene under transcriptional control of the nestin promoter, which is frequently upregulated in gliomas." (PMID 33322507, 2020). "The present immunohistochemical analysis revealed upregulation of Prox1 and HIF‐1α in some glioma tissues as well as the differentiation of nestin+ tumor stem cells into LYVE‐1+ lymphatic vessels." (PMID 31960509, 2020). "We calculated a second, separate immunocytochemical measure of tumor infiltration by quantifying high-grade glioma cells that were positive for either nestin or for IDH1 (R132H) mutant protein at the core and tumor edge." (PMID 32226940, 2020).
glioma (continued). "To analyze which cells co-localized with CCL2+ or CXL10+ cells in the glioma model, we used the stem cell marker Nestin, a microglia marker Iba-1, and the M1- and M2-type monocyte macrophage markers CD16 and CD163, respectively." (PMID 32943658, 2020). "Nestin+ cells were scattered throughout the gliomas, and some lymphatic cells also expressed nestin." (PMID 31960509, 2020). "Altogether, results indicate that FRAT1 enhances the proliferation, colony formation, sphere formation and tumorigenesity of CD133+Nestin+ glioma stem cells in vitro and in vivo as well as the expression of β-catenin." (PMID 32201513, 2020). "Aberrantly increased expression of nestin has been detected in various human malignant neoplasms, such as breast cancer, gliomas, melanomas, prostate cancer, gastrointestinal cancer and other cancer types." (PMID 32467665, 2020). "When human glioma stem cells were intracranially injected with TAT-Cx43266–283 into immunodeficient mice, there was reduced expression of the stemness markers nestin and Sox2 in human glioma cells at 7 days post-implantation." (PMID 31883012, 2020). "No nestin+ cells were observed in normal brain tissue, whereas nestin+ cells were scattered within the glioma tissues, with some forming a capillary‐like vessel structure." (PMID 31960509, 2020). "The Skp2 suppression delayed cell proliferation, sphere formation, and tumorigenesis, while the enhancement of Skp2 increased stem cell markers Nestin and Sox2 in glioma." (PMID 32165861, 2020). "Another biomarker which is regarded as glioma stem cell marker is Nestin, a type VI intermediate filament." (PMID 32160197, 2020). "qPCR analyses confirmed upregulation of Pdgfra, Olig2, Nestin, and Gfap in gliomas, compared with matched normal brain tissue from control littermates." (PMID 32142668, 2020). "CD133 accompanying with other neural and hematopoietic stem cell marker including Musashi-1, Nestin, Sox2, and Olig2 can identify glioma stem cells from different molecular subtypes of glioma." (PMID 32695001, 2020). "Glioma stem cells (GSCs) represent a subpopulation of cells in glioma that have biological characteristics similar to neural stem cells, such as differentiation into neurons, expression of nestin, CD133, and other neural stem cell surface markers." (PMID 32710727, 2020). "In summary, we observed up‐regulated co‐expression of Prox1 and HIF‐1α in gliomas as well as the differentiation of nestin+ tumor stem cells into LYVE‐1+ lymphatic endothelial cells that formed lymphatic vessels." (PMID 31960509, 2020). "These cells were identified by immunofluorescence staining with GFAP and Nestin antibody, two known glioma molecular makers." (PMID 30082910, 2019). "Sox2 and Nestin are enriched in glioma stem-like cells and maintain the cells’ stemness property and continued tumorigenicity." (PMID 31027305, 2019). "In the studies included in such systematic review, the amount of CD133+ and Nestin+ cells in human gliomas ranged between 0.5 and over 82% and between 1–100%, respectively." (PMID 31511246, 2019). "This includes the effect of the observed overexpressions, like spastin, vimentin, nestin, actin cross-linkers, etc., on migration and the underlying mechanisms, but also how migration associated signaling is altered in glioma and whether this can be used for specifically targeting glioma migration." (PMID 31003495, 2019). "The glioma stem-like cells are generally believed to express stemness and self-renewal markers, such as Sox2 and Nestin." (PMID 31027305, 2019). "Many of the key markers that emerged in the 1990s, such as nestin (Nes), were found to be widely expressed in gliomas." (PMID 31519690, 2019).
glioma (continued). "In glioma, nestin-positive cells that mark a stem-cell-like population allow tumor cells to survive and propagate upon exposure to a chemotherapeutic agent." (PMID 31126068, 2019). "As previous reports have shown that BMP signaling directs astroglial differentiation in GSCs36–38, we expected that pSmad2-positive glioma cells would be enriched in stem cell markers, such as Sox2 and nestin, compared to pSmad1-positive glioma cells." (PMID 31602000, 2019). "Honokiol also dose-dependently reduced CD133 and Nestin expression, with a maximal inhibition at 60 μM in both glioma stem cells." (PMID 30587839, 2018). "In terms of common molecular signatures, both NSCs and glioma CSCs exhibit Y-box binding protein 1 (YB-1), Sox-2, Nestin and Msi1 expression which are lost upon differentiation." (PMID 30510501, 2018). "We investigate the expression of Notch-1, OPN and vascular endothelial growth factor (VEGF) associated to the stemness markers nestin and CD133 in three stages of murine gliomas induced by N-ethyl-N-nitrosourea (ENU)." (PMID 30140373, 2018). "This analysis also indicated that patients with higher nestin expression are prone to recurrence and glioma cell infiltration into intact brain tissue." (PMID 30123089, 2018). "This marker, the membrane form of Nestin, a type VI intermediate intermediate filament protein, was initially observed on murine glioma cancer stem cells." (PMID 30279357, 2018). "EPN cells also express low levels of CD133 (a glioma stem cell marker), nestin (a marker of immature neural stem cells), CXCR4 (CXC receptor 4, which is involved in tumor migration) and SSEA-3 (stage-specific embryonic antigen 3)." (PMID 29774098, 2018). "In this study, we investigate the association between two molecules involved in glioma neoangiogenesis, OPN and Notch-1, and two stem cell markers, nestin and CD133." (PMID 30140373, 2018). "The elimination effect of GSCs in the brain glioma-bearing mice was evaluated by observing the brain sections in which nestin was used as biomarker of glioma stem cells." (PMID 28615716, 2017). "CD133+/CD15+/NESTIN+ glioma cells formed from CD133−/CD15−/NESTIN− cells after hypoxia treatment for 14 d were cultured in 1%O2, 21%O2 and 95%O2 for 48 h, and the changes in the cell cycle were subsequently detected." (PMID 28801626, 2017). "The majority of C6 glioma cells strongly expressed nestin and oligodendrocyte precursor cell markers such as PDGFR-α, NG-2, and Olig2, but not the neuron-specific marker Tuj1." (PMID 29161257, 2017). "Knockdown of lncTCF7 decreased the expression of Nestin, indicating lncTCF7 is important for glioma cells to maintain stemness." (PMID 29234033, 2017). "The results demonstrated that the expression ratios of ABCG2, CXCR4 and nestin were higher on glioma stem cells than on brain glioma cells." (PMID 28615716, 2017). "Figure 3B1-3B2 demonstrated that the expression rate of Nestin in C6 glioma stem cells was 98.51% compared to isotype contrast." (PMID 28969057, 2017). "Because NTN1 expression correlated with nestin positivity in human glioma TMA we analyzed nestin expression in the GBM xenografts." (PMID 28069038, 2017). "Although the biomarkers for identifying cancer stem cells remain controversial, nestin (Fig. 2A1,2) is considered as a characteristic marker for identifying glioma stem cells." (PMID 28615716, 2017). "Coaxial bioprinted tumor fibers had high expression of the glioma stem/progenitor cell biomarker Nestin, mesenchymal stem cell biomarkers CD44 and Vimentin comparing to the cells mixed in alginate hydrogel." (PMID 28469183, 2017). "The expression of ATP-binding cassette subfamily G member 2 (ABCG2), chemokine receptor type 4 (CXCR4) and nestin were identified on human brain glioma cells and glioma stem cells (GSCs)." (PMID 28615716, 2017).
glioma (continued). "The results displayed that serum-free medium was better for highly expression of Nestin in C6 glioma stem cell spheres, which proved this culture condition to be a proper way for the growing and proliferation of C6 glioma stem cells." (PMID 28969057, 2017). "We also observed a correlation between nestin, a stem/progenitor marker, and fibronectin, an extracellular matrix protein, expression in high grade glioma tissues." (PMID 27541285, 2017). "And the results showed that the Nestin expression level was 98.51%, which demonstrated that this preparation method of monoclonal C6 glioma stem cell spheres met the requirement of this research." (PMID 28969057, 2017). "Research elucidated that high expression of Nestin+ performed in glioma spheres cultured with growth factor, while CD133+ are obviously detected under confocal microscope after immunocytochemical staining." (PMID 28969057, 2017). "One such marker is the intermediate filament protein, nestin, which has been extensively studied in human glioma and neural stem cells." (PMID 29062039, 2017). "After LPS stimulation, the mRNA and protein levels of CD133, Nanog, and Nestin increased in glioma CD133+ CSCs." (PMID 28881826, 2017). "The closest mouse model to BarTeL is the nestin-Tva mouse, which, due to the widespread expression of nestin in stem-like cells throughout the central nervous system, has been very useful in inducing glioblastomas, medulloblastomas and brain stem gliomas." (PMID 27310018, 2016). "Human A-172 glioma cells undergo growth arrest after suppression of Nestin, and astrocytoma cells cease to grow after treatment with siRNA against Nestin." (PMID 27894083, 2016). "For example, overexpression of miR-124 reduced neurosphere formation, CD133+ cell subpopulations, and stem cell markers such as BMI1, Nanog, and nestin in glioma cells." (PMID 27824145, 2016). "In this study we combined the tumor cell specific markers in a double immunofluorescence protocol with the following panel of stem cell markers: CD133, Nestin, Musashi-1, Sox-2 and Bmi-1, to characterize the phenotype of migrating glioma cells." (PMID 27171431, 2016). "The number of glioma stem-like cells decreased after neoadjuvant Bev, however, there were still numerous nestin-positive cells predominantly around vessels." (PMID 27244880, 2016). "A recent report has shown that in human A172 glioma cells, Nestin acts to keep cells in a highly proliferative state by sequestering the glucocorticoid receptor (GR) within the cell cytoplasm." (PMID 27894083, 2016). "Nestin expression was significantly reduced in the periphery for tumor grade II and IV and for all gliomas together." (PMID 27171431, 2016). "In the PDGFR-induced glioma model, nitric oxide-mediated expression of Nestin, Notch, and NO leads to stem-like characteristics in glioma cells, which enhance tumorigenic capacities in vivo." (PMID 27891292, 2016). "FGF-2 is effective at inducing Nestin, in C6 glioma cells, proving its contribution to the stemness of glioma cells." (PMID 26977157, 2016). "The expression of representative glioma stem cell markers, Nestin and CD133, as determined using double immunofluorescent staining, was relatively even throughout the neurospheres cultured from mock-transfected U251 cells." (PMID 25605251, 2015). "The SVZ is an active proliferative zone within the brain and this region has previously been shown to be reactive and produce nestin and doublecortin positive neuroblasts in response to glioma." (PMID 25875288, 2015). "In normal brain or grade II gliomas, both V-ATPase G1 and nestin localize to endothelial cells of blood vessels." (PMID 26020805, 2015).
glioma (continued). "Eight eligible studies provided the estimation of the HR and 95 % CI for the correlation between Nestin expression and OS of glioma patients, among which statistically significant heterogeneity was observed (I2 = 75.8 %)." (PMID 25967234, 2015). "Conversely, high-grade gliomas displayed V-ATPase G1 and nestin upregulation in tumor cells, and expression of both proteins was decreased by BafA1." (PMID 26020805, 2015). "We performed systematically electronic and manual searches through the database of Pubmed and embase (until to December 25, 2014) for titles and abstracts which investigated the relationships between CD133 and Nestin expression and outcome of glioma patients." (PMID 25967234, 2015). "The PVA of PDGF-driven human and mouse gliomas is a complex structure, which contains a treatment-resistant, nestin-positive cancer stem-like cell population." (PMID 25987130, 2015). "Using the glioma TMA platform we found that V-ATPase subunit G1 expression was significantly correlated with nestin in GBM (n = 98, p = 0.028)." (PMID 26020805, 2015). "In human brain V-ATPase G1 immunostaining strongly resembled nestin pattern in either human glioma or normal tissues." (PMID 26020805, 2015). "CD133 and Nestin, as the markers of cancer stem cells, have recently been reported frequently in the pathogenesis and development of human gliomas." (PMID 25967234, 2015). "Some studies have reported that PDPN, CD133, and nestin expression are prognostic in glioma patients." (PMID 25580136, 2014). "There was no overlap of gCISs and minimal overlap of CISs compared to gCISs obtained from immortalized astroglial-like cells or their derivative gliomas generated from mice undergoing SB mutagenesis in the Nestin compartment." (PMID 25423036, 2014). "No single marker has been shown to be sufficient to confer stem-cell-like properties, thus a combination of different markers is used to identify and isolate CSC in glioma, including Nestin, Sox2 (SRY-related HMG-box gene 2) and Musashi-1 (Msi-1)." (PMID 25121761, 2014). "Nestin expression was drastically reduced in DCA-treated glioma spheroids, whereas that of Tuj and Rip was markedly increased upon this treatment." (PMID 24481450, 2014). "Although a Nestin+ cell is a candidate cell-of-origin for human glioma, the cell type(s) and the location of the cell(s) giving rise to human BSG specifically are still in question." (PMID 25330836, 2014). "The NSC protein Nestin, highly expressed in glioma andparticularly in GSC,39, 40 also appeared markedly decreased." (PMID 25429620, 2014). "In primary biopsies from lower grade gliomas, the vasculature was always nestin and SMA positive and some nestin positive reactive astrocytes were present in WHO grade II cases, whereas the actual tumor cells were variably positive." (PMID 24349039, 2013). "Nestin is expressed more frequently in higher grade gliomas, being predictive of a significantly lower 5-year survival rate." (PMID 23998913, 2013). "Gliomas from mice sacrificed 20 days after irr, however, displayed Nestin-positive cells preferentially located at tumor borders (34.6% ± 9.1% in the periphery and 10.6% ± 1.3% in the center)." (PMID 24052948, 2013). "In fact, increased expression of nestin through the activation of the Notch-signaling pathway has been detected in glioma cell lines." (PMID 23476653, 2013). "qPCR was used to study the transcription levels of Nestin, Bmi-1 and Sox2 in C6 glioma cells under various concentrations of melatonin." (PMID 24137328, 2013). "The alterations in the mRNA transcript levels of these cell proliferation markers with respect to the concentration of melatonin were similar to the changes in the cell morphology of glioma cells and the distribution pattern of Nestin expression." (PMID 24137328, 2013). "CD133 and nestin have been demonstrated to exhibit identical expression levels in both glioma cancer stem cells and normal neural stem cells." (PMID 23604326, 2013).